GNPNAT1 (glucosamine-phosphate N-acetyltransferase 1)
Synonyms: GNA1; Gpnat1; FLJ10607; GNPNAT; RHZDAN
Tractability: Small molecule: a structure with a bound ligand is known; it has a binding pocket of medium quality. Antibody: UniProt places it where antibodies can reach, with medium confidence. PROTAC: ubiquitination databases record sites on it; its protein half-life has been measured.
Gene: Protein-coding gene on chromosome 14 (52,770,976 to 52,791,668, reverse strand). Ensembl gene ENSG00000100522.
Subcellular location: Golgi apparatus membrane; Endosome membrane
Pathways (Reactome):
Metabolism of proteins: Synthesis of UDP-N-acetyl-glucosamine
Gene Ontology:
Molecular function: glucosamine 6-phosphate N-acetyltransferase activity; identical protein binding; protein binding; acyltransferase activity, transferring groups other than amino-acyl groups
Biological process: UDP-N-acetylglucosamine biosynthetic process
Cellular component: cytosol; cytoplasm; endosome membrane; Golgi membrane
Homologues: Orthologues: chimpanzee GNPNAT1 (100% identical), macaque GNPNAT1 (100% identical), dog GNPNAT1 (99% identical), pig GNPNAT1 (99% identical), mouse Gnpnat1 (98% identical), guinea pig GNPNAT1 (98% identical), zebrafish gnpnat1 (78% identical), rat AABR07059877.1 (75% identical), tropical clawed frog gnpnat1 (73% identical), Drosophila melanogaster Gnpnat (47% identical), Caenorhabditis elegans gna-2 (41% identical), Caenorhabditis elegans gna-1 (40% identical).
Diseases named in the same sentence as GNPNAT1 in open-access papers:
GNPNAT1 is named in the same sentence as 24 diseases in open-access papers, as found by Europe PMC text mining. Sharing a sentence is not in itself a finding about the gene and the disease. The quoted sentences say what the papers report.
lung carcinoma (11 papers, 2019 to 2023). "High expression of GNPNAT1 was reported in lung cancer and was associated with poor survival rate of patients with lung cancer." (PMID 37838167, 2023). "Moreover, GNPNAT1 is associated with immune signaling and is involved in lung cancer immune evasion." (PMID 36408131, 2022). "In addition, GNPNAT1 is associated with immune infiltration in lung cancer, which has a converse correlation with infiltration of B cells, CD4+ T cells, and dendritic cells, all of which have antitumor effects in NSCLC." (PMID 36408131, 2022). "Firstly, the association between GNPNAT1 and tumor-infiltrating immune cells in lung cancer was acquired via cancer database and bioinformatics analysis methods, it is necessary for researchers to further explore the immune regulatory function of GNPNAT1 in vivo and in vitro experiments." (PMID 33842535, 2021). "High glucosamine-phosphate N-acetyltransferase 1 (GNPNAT1) expression predicted poor prognosis in lung cancer and breast cancer, but was also observed in radiotherapy-sensitive breast cancer cells." (PMID 37033959, 2023). "Recently, studies have shown that abnormal expression of GNPNAT1 is related to the carcinogenesis of lung cancer." (PMID 36408131, 2022). "Patients with high expression of GNPNAT1 are more likely to develop advanced lung cancer, with a poor prognosis and low survival rate." (PMID 36408131, 2022). "In conclusion, GNPNAT1 can be used as a potential prognostic biomarker and a new immunotherapy target for lung cancer." (PMID 36408131, 2022). "Downregulation of GNPNAT1 expression has been found to be the key reason for the inhibition of lung cancer A549 cell proliferation and adhesion." (PMID 33686019, 2021). "There were five cohort meta-analyses of the differential expression of GNPNAT1 in the Lung Cancer Explorer (LCE) database, showing that the mRNA GNPNAT1 expression level was significantly higher in LUAD tumor tissues than in normal tissues." (PMID 33686019, 2021). "This study provided multiple levels of evidence for the importance of GNPNAT1 in the development of lung cancer and its potential as a biomarker and prognostic predictor of LUAD." (PMID 33178836, 2020). "The expression level of GNPNAT1 is related to the clinical stage and prognosis of lung cancer." (PMID 36408131, 2022). "Also, researchers observed that GNPNAT1 was significantly up-regulated in prostate cancer, and GNPNAT1 low expression led to reduced proliferation of tumor cells in lung cancer receiving chemotherapy." (PMID 33842535, 2021). "In the future, we will investigate the effect of GNPNAT1 on lung cancer cells through invasion and migration experiments in vitro, verify the regulatory relationship between GNPANT1 and miRNA-30d-3p and finally propose to explore the effect of GNPNAT1 on lung cancer through animal models." (PMID 33842535, 2021). "We also found that GNPNAT1 has a potential novel immunomodulatory role in LUAD tumor immunity, and it might be a new target for lung cancer immunotherapy in the future." (PMID 33686019, 2021). "However, little is known regarding the specific functions of GNPNAT1 and HBP in lung cancer." (PMID 36699466, 2022). "GNPNAT1, also known as GNA1, was a key member involved in the biosynthesis about acetylglucosamine and it was confirmed that the underexpression of GNPNAT1 could result in the inhibition of infiltration and adhesion of lung cancer cells." (PMID 32684932, 2020).
lung adenocarcinoma (8 papers, 2020 to 2025). A carcinoma that arises from the lung and is characterized by the presence of malignant glandular epithelial cells. "Furthermore, researchers proved that GNPNAT1 is a promising diagnostic and prognostic biomarker and correlates with immune infiltration in lung adenocarcinoma." (PMID 37215111, 2023). "In the previous study, researchers observed that GNPNAT1 was significantly up-regulated in lung adenocarcinoma, and overexpression of GNPNAT1 led to promote proliferative and metastatic ability of A549, a non-small cell lung cancer cells." (PMID 37215111, 2023). "Glucosamine 6-phosphate N-acetyltransferase (GNPNAT1), which serves as a critical enzyme in hexosamine biosynthetic pathway (HBP), has been identified as a metastasis-associated gene and is upregulated in lung adenocarcinoma (LUAD)." (PMID 39062049, 2024). "Though relatively fewer studies on another two HBP genes, GNPNAT1 and PGM3, the overexpression of GNPNAT1 and PGM3 was reported in lung adenocarcinoma and prostate cancer, respectively." (PMID 36158580, 2022). "However, the role of GNPNAT1 in lung adenocarcinoma (LUAD) remains unclear." (PMID 33178836, 2020). "Glucosamine 6-phosphate N-acetyltransferase (GNPNAT1) is a key enzyme in the hexosamine biosynthetic pathway (HBP), which functions as promoting proliferation in some tumors, yet its potential biological function and mechanism in lung adenocarcinoma (LUAD) have not been explored." (PMID 33842535, 2021).
prostate carcinoma (8 papers, 2019 to 2022). A carcinoma that arises from epithelial cells of the prostate gland. "GNPNAT1 expression has been linked with prognosis in prostate cancer; higher expression levels have been associated with a lower risk of biochemical recurrence, whereas lower levels are typically seen in advanced, castrate-resistant prostate cancer when compared to localised disease." (PMID 34442440, 2021). "GNPNAT1 is increased in prostate cancer compared with normal tissue but GNPNAT1 level decreases as tumors become castration-resistant, indicating stage-specific roles of HBP during prostate cancer progression." (PMID 35201498, 2021). "A recent study showed that prostate cancer contains higher levels of GNPNAT1 and UAP1 transcripts than benign tissue." (PMID 33178836, 2020). "Compared to benign tissue, prostate cancers contained elevated levels of GNPNAT1 and UAP1 transcripts, which was consistent with increased activity of HBP in matched tumor–benign pairs as detected when levels of UDP-GlcNAc were measured." (PMID 31272438, 2019). "Furthermore, researchers have shown that GNPNAT1 was upregulated in breast cancer and prostate cancer, which were related to tumor proliferation and metastasis." (PMID 33842535, 2021). "GNPNAT1 was only reported in prostate cancer, which was suggested to be over-expressed in prostate cancer tissue and to be connected with the development of castrationresistant prostate cancer." (PMID 34787244, 2021). "In prostate cancer, both GNPNAT1 and UAP1 are highly expressed at the RNA and protein levels." (PMID 33178836, 2020). "GNPNAT1 was located at chromosome 14q22.1, and our study illustrated that the DNA amplification of GNPNAT1 had a close correlation with its overexpression (P < 0.05), which was consistent with one research that the region of 14q22-q24 was significantly amplified in prostate cancer." (PMID 33842535, 2021). "In prostate cancer, GNPNAT1 and UAP1 are found to be highly expressed at the RNA and protein levels and high UDP-GlcNAc levels correlate with increased UAP1 protein levels in prostate cancer cells." (PMID 31272438, 2019). "Besides, the mRNA and protein levels of GNPNAT1 and UAP1, as well as the ratio of the intermediate metabolites (GlcNAc-6-P/GlcN-6-P), are significantly elevated in prostate cancers, compared with benign prostatic hyperplasia." (PMID 36158580, 2022). "Paradoxically, castration-resistant prostate cancers were found to have decreased HBP metabolites and GNPNAT1 expression, suggesting metabolic re-wiring may occur during prostate cancer progression." (PMID 31272438, 2019).
breast carcinoma (5 papers, 2019 to 2024). "Since GNPNAT1 was differentially expressed between breast cancer and normal tissues, we considered whether GNPNAT1 had potential diagnostic and prognostic value in BRCA." (PMID 37215111, 2023). "Studies on breast cancer have demonstrated a positive correlation between GNPNAT1 upregulation and poor patient prognosis, along with a negative correlation with immune infiltration." (PMID 39062049, 2024). "Similar to this, our in vitro experiments have confirmed that knocking down GNPNAT1 in breast cancer cell lines results in reduced proliferation and invasion capabilities of breast cancer cells." (PMID 37215111, 2023). "The significant up-regulation of GNPNAT1 expression was found in breast cancer tissues compared with normal tissues." (PMID 37215111, 2023). "The results indicated that mRNA and protein expression level of GNPNAT1 was significantly elevated in breast cancer cell lines compared with mammary epithelial cell line." (PMID 37215111, 2023). "Similar to these, our in vitro experiments have indicated that knocking down GNPNAT1 in breast cancer cell lines results in decreased proliferation and invasion capabilities of breast cancer cells." (PMID 37215111, 2023). "The IHC staining was carried out on a cohort comprising 16 cases of primary breast cancer tissues paired with para-tumor tissues, and the expression of GNPNAT1 was up-regulated in 87.5% (14/16) of breast cancer tissues via IHC optical density score." (PMID 37215111, 2023). "Additionally, Knockdown of GNPNAT1 impairs the proliferation and invasion abilities of breast cancer cells." (PMID 37215111, 2023). "Finally, Western blot, Cell counting kit-8 and Transwell assay were used to determine the proliferation and invasion abilities of breast cancer cells with GNPNAT1 knockdown." (PMID 37215111, 2023). "Additionally, intracellular levels of GNPNAT1 in ER positive breast cancer cell lines had the potential to predict sensitivity to radiotherapy." (PMID 37215111, 2023). "Knockdown of GNPNAT1 impairs the proliferation and invasion abilities of breast cancer cells." (PMID 37215111, 2023). "Notably, GNPNAT1 deletion has been shown to reduce breast cancer cell proliferation and invasion." (PMID 39062049, 2024). "In addition, GNPNAT1 was also highly expressed in 113 paired breast cancer tissues." (PMID 37215111, 2023). "Emerging evidence suggests aberrant GNPNAT1 expression in various cancers, including castrated-resistant prostate cancer (CRPC), breast cancer (BC) and LUAD." (PMID 39062049, 2024). "Glucosamine 6-phosphate N-acetyltransferase (GNPNAT1) is a crucial enzyme involving hexosamine biosynthesis pathway and is upregulated in breast cancer (BRCA)." (PMID 37215111, 2023). "To further identify the expression of GNPNAT1, we conducted qRT-PCR and Western blot on different cell lines, including one non-transformed mammary epithelial cell line and six breast cancer cell lines." (PMID 37215111, 2023).
type 2 diabetes (3 papers, 2011 to 2020). "In recent EWASs, around 60% of the methylation changes associated with age in pancreatic islets also occur in blood, including FHL2, KLF14, FAM123C and GNPNAT1, all genes known to be associated with type 2 diabetes or insulin secretion." (PMID 29164275, 2018). "Early studies have shown that GNPNAT1 deficiency may reduce insulin secretion associated with type 2 diabetes." (PMID 33178836, 2020).
diabetes (2 papers, 2016 to 2021). "Previous studies have shown that GNPNAT1 is associated with insulin secretion and diabetes." (PMID 33661921, 2021). "In addition, methylation of KLF14, FHL2 and GNPNAT1 was associated with lower diabetes risk in the Botnia prospective study." (PMID 27029739, 2016).
cervical cancer (1 paper, 2023). A primary or metastatic malignant neoplasm involving the cervix. "In particular, seven genes showed higher expression in cervical cancer and positively correlated with EMT scores, including CSRP2BP, LPCAT1, NAT14, CREBBP, MSL3, ATF2 and GNPNAT1." (PMID 37845756, 2023).
congenital myasthenic syndrome (1 paper, 2023). Congenital myasthenic syndrome (CMS) is a group of genetic disorders of impaired neuromuscular transmission at the motor endplate characterized by fatigable muscle weakness. "Some examples of other (including multiple) glycosylation pathway defects discovered in the last five years are ATP6VI1-, GO7- (Congenital myasthenic syndrome), GET4-, GFUS- and GNPNAT1-CDG, and most recently CAMLG-CDG." (PMID 37858231, 2023).
lymph node metastasis (1 paper, 2021). "In this study, our results indicated that GNPNAT1 was increased in various tumors, including LUAD, and its overexpression was related to advanced staging, lymph node metastasis, and poor prognosis." (PMID 33842535, 2021).
tumor (16 papers, 2020 to 2025). "Correlation analysis revealed a positive association between GNPNAT1 expression and clinicopathological characteristics, including tumor stage, lymph node metastasis, and clinical stage (TNM stage)." (PMID 39062049, 2024). "Based on the ROC analyses, the diagnostic efficacy of GNPNAT1 was proved in different cohorts, and AUC value highlighted the significant differences between the normal tissues and different tumor stages." (PMID 37215111, 2023). "GNPNAT1 showed 1.659 times higher risk on overall survival and can predict tumor outcomes independently of the other six immune cells (HR = 1.659, 95%CI = 1.343‐2.049, p value = 0)." (PMID 33178836, 2020). "To summarize, these results showed that GNPNAT1 might be associated with tumor progression and regional lymph node metastasis in BRCA patients, and knockdown of GNPNAT1 impairs the proliferation and invasion abilities of BRCA in vitro." (PMID 37215111, 2023). "In conclusion, our findings demonstrate that GNPNAT1 is highly expressed in LUAD and is associated with immune regulation within the tumor microenvironment." (PMID 39062049, 2024). "Collectively, these results suggest that GNPNAT1 plays a crucial regulatory role in the tumor immune microenvironment and the development of LUAD." (PMID 39062049, 2024). "The mRNA expression level of the GNPNAT1 was significantly correlated with the stage, tumor stage and node stage, but it was nothing to do with metastasis stage." (PMID 37215111, 2023). "Taken together, the expression of GNPNAT1 was negatively associated with immune cell recruitment in BRCA, which possibly altered the composition of immune cells in the tumor environment and thereby affected the progression of BRCA patients." (PMID 37215111, 2023). "Initially, Comparing GNPNAT1 expression between normal tissues and tumor samples from TCGA database, we found that GNPNAT1 was significantly up-regulated in many types of cancer, including BRCA." (PMID 37215111, 2023). "Glucosamine 6-phosphateN-acetyltransferase 1 (GNPNAT1) is a key enzyme in the hexosamine biosynthetic pathway, which is abnormally expressed in tumor cells and promotes tumor progression and metastasis." (PMID 36408131, 2022). "In this study, the tumor metabolism gene GNPNAT1 expression was closely related to immune cell infiltration in LUAD and was correlated with immunomodulators and chemokines." (PMID 33686019, 2021). "Tumor IMmune Estimation Resource results noted that GNPNAT1 expression was negatively correlated with B cells (R = −0.304, P = 8.04e-12), CD4+ T cells (R = −0.218, P = 1.24e-06), and dendritic cells (R = −0.137, P = 0.002)." (PMID 33842535, 2021). "In all subgroups, the mRNA GNPNAT1 expression level was higher in LUAD tumor tissues than in normal tissues." (PMID 33686019, 2021). "The association between GNPNAT1 expression and tumor-infiltrating immune cells in LUAD was observed through the Tumor IMmune Estimation Resource (TIMER)." (PMID 33842535, 2021). "We analyzed multiple lung adenocarcinoma (LUAD) gene expression databases and verified GNPNAT1 higher expression in LUAD tumor tissues than in normal tissues." (PMID 33686019, 2021). "GNPNAT1 was expressed at higher levels in LUAD tumor tissues than in normal tissues, which makes GNPNAT1 a potential biomarker in LUAD." (PMID 33686019, 2021). "Correlate analysis provides an exhaustive characterization of the association between GNPNAT1 and immune signatures in LUAD patients, indicating that GNPNAT1 is a crucial player in immune escape in the tumor microenvironment." (PMID 33178836, 2020). "In our story, the investigation of differential expression in LUAD indicated that GNPNAT1 was highly expressed in tumor tissues, which was subsequently validated in two independent GEO datasets." (PMID 33178836, 2020).